FOXO4 (forkhead box O4)
Diseases named in the same sentence as FOXO4 in open-access papers (continued):
Sharing a sentence is not in itself a finding about the gene and the disease.
cancer (continued). "FOXO4, as a member of the FOXO family of transcription factors, is regulated by microRNA in a variety of cancer cells, and its abnormal expression is closely related to gastrointestinal tumors." (PMID 33381024, 2020). "EGFR signaling is highly activated in cancer;therefore, we sought to determine the dynamics of EGFR activation and FOXO4 regulation." (PMID 33101846, 2020). "The top-ranked miRNAs (mir-199, mir-29, mir-200) and transcription factors (FOXO4, E2A, NFAT, and MAZ) were identified, which play an important role in deregulating cellular energetics; and regulating angiogenesis and cancer immune system." (PMID 29348878, 2017). "It has been demonstrated that the mRNA level and protein expression of the FOXO4 gene in BC tissues are significantly lower than those in normal bladder tissues adjacent to cancer." (PMID 41438489, 2025). "Here, we evaluated the expression, prognostic value, mutation, methylation, and clinical features of four FOXO family genes (FOXO1, FOXO3, FOXO4, and FOXO6) in 33 types of cancers based on the Cancer Genome Atlas (TCGA) and Genotype Tissue Expression (GTEx) databases." (PMID 36555288, 2022). "This study provides insight into FOXO4 upstream regulatory circuit and elucidates how oncogenical signal in interfering FOXO4's downstream inhibitory activity toward SGOC pathway to promote cancer development." (PMID 33101846, 2020). "However, the FOXO4‐SGOC pathway link is identified for the first time, adding another layer of FOXO4's role in controlling cancer metabolism reprogramming." (PMID 33101846, 2020). "This suggests a dominant role of protein degradation, rather than nuclear export, in the regulation of FOXO4 proteostasis in these RAS-mutant cancer cells." (PMID 28945225, 2018). "FOXOs, comprising FOXO1, FOXO3, FOXO4, and FOXO6, are the focus of cancer research recently." (PMID 30046342, 2018). "Given that the proteasome was identified as a common target in multiple oncogenic RAS synthetic lethal genetic screens, we hypothesized that RAS-mutant cancer cells also enhance proteasome activity to maintain proper proteostasis and to eradicate growth suppressors like FOXO3A and FOXO4." (PMID 28945225, 2018). "In addition, members of the FOXO family, such as FOXO1, FOXO3, FOXO4, and FOXO6, have been found to participate in various physiological responses, such as DNA damage, caloric restriction and oxidative stress, and play crucial roles in cancer initiation, progression, and chemo‐resistance." (PMID 32368828, 2020).
infection (5 papers, 2008 to 2022). The state of being infected such as from the introduction of a foreign agent such as serum, vaccine, antigenic substance or organism. "Seven days after infection, as expected, FoxO4-cKO mice showed significantly reduced bacterial burdens in the liver and spleen compared with WT mice, indicating that the FoxO4-cKO mice were more resistant to L.monocytogenes infection." (PMID 36106640, 2022). "To investigate the role of FOXO4 in GC growth, we established two stable cell lines (denoted SGC7901-FoxO4 and SGC7901-NC) after infection with the LV- FoxO4 or LV-NC lentivirus, respectively." (PMID 24886657, 2014). "FoxO4 levels were steadily increased through the time of infection." (PMID 36016282, 2022). "In contrast, infection with the vector encoding Lef1 greatly augmented IFN-γ expression in DKK3-treated FoxO4-cKO cells compared with FoxO4-cKO cells under Th1-polarizing conditions, indicating that ectopic Lef1 expression in FoxO4-cKO cells could rescue IFN-γ expression after DKK3 treatment." (PMID 36106640, 2022). "The transcriptome analysis showed an increase in FoxO1 and FoxO3 mRNAs early in infection (4 h.p.i.), however, the results were somewhat inconclusive for the FoxO4 transcript due to the low number of the reads (not shown)." (PMID 36016282, 2022).
adenocarcinoma (1 paper, 2025). A common cancer characterized by the presence of malignant glandular cells. "Additionally, FOXO4 exhibited a significant decline in all adenocarcinomas (p = 0.001) as well as in 68% of paired samples (p = 0.00004)." (PMID 40699620, 2025).
bacterial infection (1 paper, 2022). "Loss of FoxO4 enhances Th1 cell–mediated immunity to bacterial infection." (PMID 36106640, 2022). "Thus, loss of FoxO4 enhanced Th1 cell–mediated immunity to bacterial infection in vivo." (PMID 36106640, 2022). "Taken together, our findings indicate that FoxO4 serves as a negative regulator of antigen-specific Th1 cell responses to bacterial infection." (PMID 36106640, 2022).
inflammation (1 paper, 2017). Aberrant reaction of the microcirculation characterized by movement of fluid and leukocytes from the blood into extravascular tissues. "Furthermore, Foxo4 only reversed the upregulation of MC5R and Leptin (P<0.05), and the downregulation of Foxo4 and IL-6 by αMSH in mRNA level (P<0.05), suggesting that αMSH may inhibit adipocyte inflammation partly via Foxo4 transcriptional regulation." (PMID 28514752, 2017).
neurological diseases (1 paper, 2013). "So, by combining specific GO term–annotated gene lists and cross-checking with publications, we were able to decrease the number of candidate genes and predict candidate genes (FOXO4, GRM5, RIMS1 and NELL2) for neurological diseases." (PMID 23794737, 2013).
FOXO4 also shares sentences with these, for which no sentence is quoted: acute leukemia (5 papers); alveolar rhabdomyosarcoma (3); breast tumors (3); thymic lymphomas (3); acute lymphoblastic leukemia (2); acute myocardial infarction (2); asthma (2); cardiovascular disease (2); clear cell renal carcinoma (2); lung adenocarcinoma (2); maturity-onset diabetes of (2); myocardial ischemia (2); acute promyelocytic leukemia (1); aneurysm (1); calcium oxalate kidney stones (1); cardiac diseases (1); COVID-19 (1); cutaneous melanoma (1); disc degeneration (1); gastrointestinal tumors (1); hematological malignancies (1); Hypocalcemia (1); infarction (1); infectious disease (1); invasive breast carcinoma (1); ischemic stroke (1); Kawasaki disease (1); lymphocytic leukemia (1); lymphoid neoplasm (1); myopathy (1).
A further 15 diseases each share a sentence with FOXO4 in 1 paper.